TERT (telomerase reverse transcriptase)
Diseases named in the same sentence as TERT in open-access papers (continued):
Sharing a sentence is not in itself a finding about the gene and the disease.
tumor (continued). "Three shared somatic mutation genes were identified between the tumor and the CSF, namely TERT, PI3KCB, and CDKN2A." (PMID 37822669, 2023). "In particular, BRAF and TERT promoter co-mutations were more commonly detected in male patients at an older age, that had a larger tumor size and were more prone to extra-thyroid invasion." (PMID 37046812, 2023). "The only recurrent mutation analysed in the cohort was the TERT promoter mutation C228T, which highlights the need to perform genetic testing on tumour material to select patient-specific genetic variants for monitoring tests." (PMID 37721600, 2023). "CLNM in cN0 PTMC patients is associated with male sex, tumor size, extrathyroidal extension, HT, TERT promoter mutations and NRAS mutation." (PMID 36817603, 2023). "TERT promoter mutations have been recognized as an early marker of tumour development or a major indicator of poor outcome and reduced patients survival in several cancer types." (PMID 38033865, 2023). "survival times; correction rates of the DNA region spanning the -124C>T mutation in the TERT promoter of the combined tumor tissues; telomere length; expression levels of TERT, Ki67 and cleaved PARP1; cell proliferation assay." (PMID 37008065, 2023). "TERT mutations have been shown to be positively correlated with a higher tumour mutational burden (TMB) value, neoantigen load, and tumour purity." (PMID 36612301, 2023). "Their two studies found a nine-fold and five-fold lower uptake in tumours harbouring TERT promoter mutations." (PMID 37352166, 2023). "Immunomonitoring showed induction of neoantigen and NY-ESO1 and TERT blood tumor-specific T cell response associated with better PFS." (PMID 37563240, 2023). "We found an association between TERT mRNA expression and adaptive immune B and T cell infiltrates in multiple tumor types." (PMID 36909826, 2023). "These mutations lead to excessive expression of the TERT gene, enhancing the unrestricted proliferation and growth capacity of tumor cells." (PMID 37830090, 2023). "Only one grade 2 PXA case was identified with a TERT promoter mutation, but the tumor recurred as grade 3 PXA within half a year." (PMID 36826144, 2023). "Next-generation sequencing revealed an APC mutation and a TERT promoter mutation in both tumor parts with the former being associated with the underlining FAP, the latter being potentially associated with an adverse outcome." (PMID 37249797, 2023). "A further study, including 1,230 cases of 60 different tumour types, demonstrated that tumours can be classified into types with low (<15%) and high (≥15%) frequencies of TERT promoter mutations." (PMID 38033865, 2023). "The results showed that sex, HT, tumor size, extrathyroidal extension, TERT promoter mutations and NRAS mutation were independent factors." (PMID 36817603, 2023). "Recent genetic profiling studies of tumor tissues have found somatic mutations in genes such as the TERT, PTEN, and epidermal growth factor receptor (EGFR)." (PMID 36359238, 2022). "TERT mutations are associated with a higher incidence of local or distant metastasis and tumor aggressiveness." (PMID 35884820, 2022). "TERT rs2736100 genetic polymorphism (TG/GG vs. TT) was significantly associated with several high-risk clinicopathological features such as tumor spread, extrathyroidal extension, central/lateral lymph node metastases, and Stage T III or IV disease." (PMID 36704521, 2022). "Specifically, the methylation of TERT promoter has become a hallmark of TERT re‐expression in multiple tumour types." (PMID 35979662, 2022).
tumor (continued). "Specifically, abstracted data from institutional and TCGA cases were reviewed to identify potential associations between TERT alteration status and clinicopathologic features such as: age at presentation, sex, tumor laterality, size and weight." (PMID 34549366, 2022). "The PuMRS high-risk group significantly had higher tumor grade, more TERT promoter mutation, less IDH mutation, less 1p/19q codeletion, less MGMT promoter methylation, and less ATRX mutation." (PMID 36438805, 2022). "Among several related tumor types, TERT promoter mutations seem to constitute a new prognostic biomarker, with potential application prospects in presurgery diagnosis and patient follow-up." (PMID 35903534, 2022). "In the emergence of HCC from CLD, TERT promoter mutations aid hepatocyte fitness and there is evidence of hypomethylation associated with upregulation of tumor-promoting genes, as well as epigenetic silencing of tumor suppressor genes." (PMID 35814741, 2022). "Telomerase reverse transcriptase (TERT) promoter mutations are associated with tumor aggressiveness." (PMID 34497362, 2022). "Several studies have shown that the prognostic significance of TERT mutations depends on age, tumor histology, surgery, IDH wild status, and unmethylated MGMT promoter status." (PMID 35806478, 2022). "Previous studies have shown the association that TERT promoter mutations are associated with tumor aggressiveness and patients survival in DTC16–18,21,30,31." (PMID 34497362, 2022). "Administration of a TERT inhibitor inhibited LATS2-mutated tumor growth in tumor-bearing mouse models." (PMID 36335095, 2022). "In comparison, 10 out of 26 tumours (38.4%) had at least 3 reads in at least 1 sequenced microdissection supporting a TERT mutation (i.e. mutation in hg19: between Chr5, positions 1,295,228 and 1,295,250)." (PMID 35739588, 2022). "We conclude that recurrent TERT promoter duplications are functionally and mechanistically equivalent to the hotspot mutations that confer tumor cell immortality." (PMID 36114166, 2022). "In patients with bladder cancer and melanoma, THOR hypermethylation combined with TERT promoter mutations are associated with an increased risk of tumour progression and with a decreased progression‐free survival." (PMID 35920280, 2022). "One of the most common mechanisms of telomerase upregulation in tumours is the presence of mutations at the TERT promoter." (PMID 35920280, 2022). "Mutations in the TERT gene promoter are among the most reported high-risk mutations, and are strongly related to tumor dedifferentiation and metastasis." (PMID 35865459, 2022). "There are many more examples in other tumor types where TERT promoter mutations can change grading or diagnosis." (PMID 36114166, 2022). "Studies have shown that transcriptional reactivation of TERT is associated with methylation and mutation of its promoter region in a variety of human tumor diseases." (PMID 35739589, 2022). "Somatic mutations in TERT promoter regions, were most frequently identified in both tumor (44%) and normal samples (61%)." (PMID 36198773, 2022). "Across the 23 patients whose tumor and urine samples were profiled (67 total samples), TERT promoter mutations were the most common." (PMID 36233691, 2022). "The 70% (21/30) of tumours with TERT expression held at least one pathogenic alteration at TERT promoter, being promoter methylation more frequent than the presence of promoter mutations (53.3%, 16/30 and 33.3%, 10/30, respectively)." (PMID 35979662, 2022). "In neoplasia development, what is the effect of TERT rs2736100 genetic polymorphism on clinical progress?" (PMID 36704521, 2022).
tumor (continued). "We validated the ChIP-seq results with ChIP-qPCR of the TERT promoter region compared to other tumour suppressor genes which are known to become mutated in later stages of hepatocellular carcinogenesis." (PMID 35739588, 2022). "A higher prevalence of recurrence was found in patients with tumor stage T3/T4 (p = 0.009), distant metastasis (p < 0.001), and TERT mutation (p = 0.011)." (PMID 36077665, 2022). "Characterization of alterations related to TERT re‐expression revealed that promoter mutations, methylation and/or copy gains exclusively co‐occurred in clinically aggressive tumours." (PMID 35979662, 2022). "Molecular findings associated with increased tumor recurrence risk such as TERT promotor mutation and CDKN2A/B deletion are seen only in a small subset of the tumors." (PMID 34601710, 2022). "Regardless of regulatory mechanisms, the mutation‐carrying TC tumours express high levels of TERT mRNA and telomerase activity." (PMID 36394204, 2022). "In vitro, telomere attrition and growth retardation can be caused by TERT haploinsufficiency in tumor cells." (PMID 35328421, 2022). "Telomerase reverse transcriptase (TERT) mutations lead to aberrantly upregulating TERT expression and ultimately enable telomere maintenance, which achieves the unlimited proliferative capacity of tumor cells." (PMID 36273184, 2022). "In one tumor, however, the percentages of the lost alleles on 1p and 19q were more than 10% lower than the expected values calculated from the TERT and IDH1 MAFs, possibly suggesting 1p/19q codeletion as the initial clonal event in this particular tumor." (PMID 35361262, 2022). "Overall, a statistically significant correlation between high VAF (higher than the mean) and tumor progression was found for the TERT c.-124C > T mutation (p = 0.019)." (PMID 35713686, 2022). "These somatic mutations are known to increase TERT expression, telomerase enzyme activity, telomere length, and tumor formation." (PMID 35888045, 2022). "In the vast majority of tumor cells, the TERT promoter is mutated to promote proliferation and inhibit apoptosis." (PMID 35053139, 2022). "Mutations that result in TERT silencing usually cause immortal cell lines to senescence or die while those that enhanced expression exhibited TERT levels comparable to tumor cell lines." (PMID 35328421, 2022). "These include methylation patterns, copy number alterations, and mutually exclusive driver mutations affecting oncogenes, including BAP1, CDKN2A/B, and the TERT promoter, which are associated with particularly aggressive tumor biology." (PMID 35299730, 2022). "According to the existing research about TERT promoter mutations and telomere, the prominent role of telomerase in human tumors promotes the development of telomerase inhibitors to inhibit tumor growth." (PMID 35903534, 2022). "In contrast, the present study showed TERT promoter mutations were significantly associated with aggressive clinico-pathological features, such as older age, extrathyroidal extension, tumor recurrence and DM." (PMID 35360077, 2022). "While both subclones consistently maintained the same TERT promoter mutation (C250T) of the original tumor and cell line, subclone #11 showed higher enzymatic activity of telomerase and TERT expression compared with subclone #5." (PMID 35278143, 2022). "In differentiated forms, TERT promoter mutations are found in ∼9% of the tumours and are associated with disease outcome." (PMID 35979662, 2022). "The knowledge of non-canonical functions activated by highly expressed telomerase would be valuable to identify new actionable targets in SCC of the lower genital tract as well as in many TERT mutated tumours." (PMID 35804458, 2022). "Mutation of the NF2 locus is also linked to TERT promoter mutations, which increase with tumor grade." (PMID 35892898, 2022).
tumor (continued). "HBV-DNA integration in the TERT gene is considered the most important hotspot of HBV integration in tumor samples and has been associated with a more aggressive tumor behavior and a significantly poorer survival." (PMID 36118192, 2022). "Recent studies have identified telomerase reverse transcriptase (TERT) promoter mutations that are closely associated with tumor aggressiveness, early recurrence, and cancer specific deaths in patients with thyroid cancer." (PMID 34497362, 2022). "The reasons that TERT upregulation negatively affects patient survival are linked to its canonical function, i.e., maintenance of telomere length with increased tumor cell survival." (PMID 35954336, 2022). "Given that ARID1A is a negative regulator of TERS, loss of its expression caused by inactivating mutations would enhance TERT transcription, conferring a survival advantage for tumor cells by maintaining their telomeres." (PMID 34791836, 2022). "We also analyzed genes involved in maintenance of telomeres, whose tumor-suppressive function is dependent on the silencing of TERT, which encodes a reverse transcriptase and core component of telomerase." (PMID 35705560, 2022). "Surprisingly, the difference in tumor size between TERT-wildtype and mutation group was also significant." (PMID 35311090, 2022). "Here, with the benefit of a large patient cohort, we show that although IDH2 tumours are more commonly associated with TERT mutations, only IDH1 mutations in combination with TERT mutations are associated with significantly reduced survival." (PMID 36042521, 2022). "High-throughput genomic sequencing is often used for the detection of TERT-p mutations, but the sensitivity is affected by the proportion of tumor cells and sequencing depth." (PMID 35495630, 2022). "Coexistence with the BRAF V600E mutation is associated with higher tumor aggressiveness in PTC than in TERT and BRAF mutations occurring alone." (PMID 35884820, 2022). "IDH wild-type tumours rarely exhibit TERT mutations and tend to be diagnosed in a younger population than those with tumours harbouring IDH1 and IDH2 mutations." (PMID 36042521, 2022). "In contrast, TERT mutations are rarer in IDH1-mutant tumours, yet they are associated with a less favourable outcome in this group." (PMID 36042521, 2022). "The results showed that PTCs with concurrent BRAF and TERT promoter mutations were associated with tumor invasiveness and that BRAF or TERT promoter mutations were less aggressive." (PMID 35777039, 2022). "TERT promoter mutation alone was associated with aggressive clinicopathologic characteristics: old age, larger tumor size, multifocal PTCs, extrathyroidal extensions, PTC variants, perinodal infiltration, distant metastasis, and stage III–IV." (PMID 36230856, 2022). "First, it has a historical, retrospective nature, it lacks complete information on some tumor features including TERT and BRAF mutations, and 3% of the patients were lost to follow-up." (PMID 35355557, 2022). "TERT promoter mutations generally occur late in tumor genesis, after the appearance of driver mutations in other oncogenes such as RAS/BRAF, EGFR, which lead to constitutive cell division and thus accelerate telomere erosion." (PMID 34944589, 2021). "Both the parent tumor and 2XSB cells had a common mutation in the core TERT promoter, C250T (− 146 bp)." (PMID 33707600, 2021). "Higher prevalence of recurrence was found in patients with tumor stage T3/T4 (p = 0.009), distant metastasis (p < 0.001), and TERT mutation (p = 0.011)." (PMID 34572876, 2021). "After multivariable regression including these four variables, only tumor grade remained significant, indicating the strong association between TERT promoter mutation and tumor grade." (PMID 34108637, 2021).
tumor (continued). "Collectively, these studies have highlighted the importance of TERT promoter mutations as a gate-keeper for TERT reactivation and tumor progression." (PMID 33483600, 2021). "In the present study, TERT promoter mutations were found in 57.9% of tumours although they were mutually exclusive." (PMID 34168209, 2021). "In line with our previous findings, TERT promoter mutations significantly associated with high tumor grade, metastasis, and disease-related mortality." (PMID 34108637, 2021). "In summary, our data identified TERT alterations, especially TERTp mutation, are associated with tumor progression and poor outcome of newly diagnosed HGM patients after postoperative RT." (PMID 34778063, 2021). "Only 13% of all tumor samples were found to have non-coding mutations involved in cancer formation – beyond those in the TERT promoter, which I will discuss separately in Sect." (PMID 34097189, 2021). "The current version of Caris® Life Sciences tumor profiling employs whole exome sequencing instead of next-generation sequencing, which allows the detection of TERT promoter mutations." (PMID 33716974, 2021). "The assay detects single nucleotide variants (SNV), indels, focal copy number alterations (CNA), TERT promoter region, as well as tumor mutation burden (TMB) and microsatellite instability (MSI) status." (PMID 33889297, 2021). "The rs401681 is a SNP located in the intron of CLPTM1L and 27 kb from the TERT gene, being associated with many tumor types." (PMID 33879152, 2021). "This suggests that there is a significant tumor heterogeneity with TERT promoter-mutated subclonal populations, but that these areas can be morphologically identified as areas with higher tumor grade." (PMID 34108637, 2021). "At univariate analysis, male sex, older age at diagnosis, type of cancer, TNM parameters, tumor stage, need for a second treatment, and TERT mutations were all associated with a worse outcome (p < 0.01)." (PMID 33790328, 2021). "Based on these analyses, the following findings were concluded: (I) tumor aggressiveness and TERT promoter mutation rates were intimately correlated." (PMID 33669363, 2021). "HepG2 has a large in-frame deletion in the CTNNB1 gene comprising 116 codons of exons 3 and 4 and a mutation of the TERT promoter and represents the fetal tumor subtype with high GLUL expression and GS abundance." (PMID 34235580, 2021). "Some studies reported that TERT promoter mutations in BC were significantly associated with higher tumor grades and stages, while others showed that TERT promoter mutations can be found in all BC stages and grades." (PMID 35223454, 2021). "TERT mutation status, tumor size, and tumor grade were independent prognostic predictors for MFS in CS patients." (PMID 34108637, 2021). "Among the 184 sequenced genes, only TERT alterations were significantly associated with tumor progression (n = 8, adjusted p = 0.031), and all these mutations were present in tumors that progressed after RT." (PMID 34778063, 2021). "A significant association between TERT promoter mutations with older age at diagnosis, tumor size, extrathyroidal invasion, vascular invasion, lymph node and distant metastasis, advanced stage and mortality has been reported." (PMID 33572167, 2021). "In the series as a whole, TERT-mutated patients were older at diagnosis (63 versus 47 years, p < 0.01), and had larger tumors (44 versus 16 mm, p < 0.01), and a greater tumor extension (T4: 11.5% versus 3.5%, p < 0.01)." (PMID 33790328, 2021). "In brain cancers, concurrent mutations of BRAF and TERT promoter have been identified to be associated with tumor aggressiveness." (PMID 33996815, 2021). "TERT C228T mutation was associated with worse clinical outcomes in some tumor types than TERT C250T mutation." (PMID 34395278, 2021).